APOE (apolipoprotein E)
Diseases named in the same sentence as APOE in open-access papers (continued):
Sharing a sentence is not in itself a finding about the gene and the disease.
atherosclerosis (continued). "For instance, although ApoE−/− mice develop atherosclerosis in the absence of a high fat diet, this condition is substantially accelerated when mice are fed a cholesterol-rich diet." (PMID 27538678, 2016). "To validate the effect of TLR5 on atherosclerosis, we injected rFliC or ΔrFliC, non-functional flagellin, into the ApoE mice with HFD." (PMID 27146088, 2016). "Nevertheless, even in the 12 weeks old mice, a significantly reduced atherosclerosis was observed in ApoE−/−Adamts4−/− male mice, albeit not in the female counterpart." (PMID 27491335, 2016). "In support of this assertion, CIA studies performed on ApoE−/− mice show no change in atherosclerosis." (PMID 27287704, 2016). "When ApoE−/− mice were compared to C57BL/6 there was a 5.2-fold increase in area of atherosclerosis in the absence of arthritis and a 3.6-fold increase in the area of atherosclerosis in the presence of arthritis." (PMID 27287704, 2016). "In ApoE−/− mice, administration of eplerenone prevented atherosclerosis progression without affecting serum cholesterol or triglyceride levels." (PMID 27277003, 2016). "Some evidences showed that increased expression of p22phox contributed to the process of atherosclerosis and apoE−/− mice lacking p47phox had a marked reduction of atherosclerosis in the descending aorta." (PMID 26180602, 2015). "Hence, our study has further demonstrated that MIF gene interference effectively inhibits atherosclerosis process and stabilizes vulnerable plaque in STZ-induced diabetic apoE−/− mice." (PMID 25661015, 2015). "In STZ-induced diabetic ApoE−/− mice, metformin failed to control blood glucose and reduce atherosclerosis." (PMID 25785279, 2015). "In ApoE-null mice, both PCA and Cy-3-G were reported to attenuate atherosclerosis." (PMID 26175728, 2015). "We conducted a proof-of-efficacy study to evaluate the effects of hydroxychloroquine in an animal model of atherosclerosis in ApoE knockout mice with and without chronic kidney disease." (PMID 26414017, 2015). "Endothelial dysfunction as measured by AUE echography has been strongly associated with the development and severity of atherosclerotic plaque in apoE-/- mice models, and blinded AUE assessment of major vasculature has excellent validity with the severity of vascular disease and atherosclerosis." (PMID 26414017, 2015). "In apoE-/- mice without kidney disease on a normal chow diet (early atherosclerosis) exercise does not affect systemic cytokine concentrations." (PMID 25799529, 2015). "pol γ-/-/ApoE-/- mice show extensive mtDNA damage, impaired mitochondrial respiration, and increased atherosclerosis, even without increased ROS." (PMID 27508052, 2015). "The lack of gut microbiota in germ-free apolipoprotein E (ApoE)-null mice, an experimental model of human atherosclerosis, was found to induce the development of atherosclerotic plaques even when animals were fed a standard low-cholesterol diet." (PMID 26175728, 2015). "Among a number of genes already known to play major roles in the development of atherosclerosis such as Ccl2 (MCP-1), Rgs1 was identified as one of the novel candidate genes with higher expression in aortas from older ApoE−/− mice than in aortas from younger ApoE−/− mice." (PMID 25782711, 2015). "The ApoE-/- mice in this study developed little atherosclerosis when maintained on the Standard diet, which does not contain sucrose or added cholesterol, and is lower in fat compared to the Western diet." (PMID 27683620, 2015).
atherosclerosis (continued). "Pioglitazone, which compared to rosiglitazone has a more favorable effect on lipid profile, reduced the lipid contents of aortic lesions without decreasing the extent of atherosclerosis in insulin resistant ApoE−/− mice (IRS2+/−ApoE−/− mice)." (PMID 25785279, 2015). "Therefore, apoE(−/−) mice fed with HFD, the classical animal model for atherosclerosis research, are often employed to explore the mechanism of NAFLD." (PMID 26697490, 2015). "The apoE mice also appear to show a lack of sensitivity toward statins, the standard therapy for patients with atherosclerosis." (PMID 25972522, 2015). "ApoAI mimetic peptide D4F (with 4 phenylalanine residues) synthesized with D-amino acids has been demonstrated to reduce atherosclerosis in apolipoprotein E (apoE)-null and LDL-receptor-null mice." (PMID 26398523, 2015). "We had previously reported that the attenuation of atherosclerosis in the DKO was accompanied by a sustained reduction in the aortic expression of MCP1, compared to that seen in the ApoE-null mice, and that this effect was dependent on the presence and the activation of PPARα." (PMID 24587793, 2014). "In conclusion, in the apoE knockout rats, occlusal disharmony may induce VCAM1, ICAM1 and TLR4 expression and accelerate the initiation of atherosclerosis." (PMID 25189624, 2014). "We report the first in vivo imaging study of VEGFR prevalence in atherosclerotic plaques in diabetic vs. non-diabetic atherosclerosis-prone ApoE−/− mice, a model where atherosclerosis is accelerated by diabetes." (PMID 26055940, 2014). "ApoE is a ligand for receptor-mediated clearance of chylomicron and VLDL remnants, which areparticles that may promote atherosclerosis directly or through the action of lipases to releasetoxic products of lipolysis (Goldberget al, 2011)." (PMID 25172365, 2014). "ApoE−/− mice that did not drink cola beverages (i.e.: W group) showed accelerated changes in atherosclerosis progression which paralleled a rapid increase in liver inflammation around the 20 weeks of age." (PMID 24670925, 2014). "The hyperlipidemia and atherosclerosis animal pathogenesis and how ApoE affects hyperlipidemia and atherosclerosis are not entirely clear." (PMID 25006576, 2014). "PAI-1 deficiency augmented atherosclerotic progression in the ApoE−/− genetic background in one study while a cross of LDL receptor-null, atherosclerosis-prone with PAI-1−/− mice did not change vessel lesion formation." (PMID 26110015, 2014). "The present study demonstrates that inhibition of NFAT-signaling completely suppresses accelerated atherosclerosis in the aortic arch of diabetic ApoE−/− mice and that this effect is independent of changes in plasma glucose or lipid levels." (PMID 23755169, 2014). "Our findings demonstrate that expression of these genes increases as part of the natural progression of atherosclerosis in ApoE-/- mice in the absence of an additional pro-atherogenic stimulus." (PMID 25540039, 2014). "ApoE-/- mice are the most widely used mouse model for the development of atherosclerosis in the absence of additional stimuli and are characterized by increased total plasma cholesterol levels." (PMID 25540039, 2014). "Although calcium and phosphate levels were not significantly elevated in ApoE-deficient SNX mice, we observed a striking correlation between phosphate and the calcium phosphate product and atherosclerosis." (PMID 24690995, 2014). "In fragments harvested from non-diabetic ApoE−/− mice with similar extent of atherosclerosis the nonspecific (non VEGFR-mediated) uptake of in-scV/Tc (0.44 ± 0.12%ID/g) was significantly lower than scV/Tc uptake (P < 0.01)." (PMID 26055940, 2014).
atherosclerosis (continued). "Deletion of ACKR3/CXCR7 in apoE−/− mice results in increased atherosclerotic lesion formation and the application of a small molecule ACK3 agonist decreases atherosclerosis by a mechanism that relates to the expression of ACK3 in white adipose tissue, where it takes part in cholesterol metabolism." (PMID 25152735, 2014). "Overexpression of RAGE in vascular endothelial cells and monocytes plays a critical role in development of atherosclerosis in nondiabetic apoE−/− mice and with the addition of diabetes atherosclerosis development is accelerated." (PMID 24829796, 2014). "We previously reported that ApoE-null mice lacking PPARα were resistant to diet-induced atherosclerosis, despite exhibiting the worsened lipid profile expected from the absence of PPARα." (PMID 24587793, 2014). "It should be emphasized that, in contrast to the effect of mepyramine, neither cetirizine nor fexofenadine, even at high doses prevented or reduced atherosclerosis progression in ApoE−/− mice." (PMID 25020133, 2014). "Although in this study, we did not image ApoE−/− mice fed with high-fat (Western) diet to accelerate atherosclerosis since the lesion histology in the diabetic mice is very similar to that of mice at the same age fed with high-fat (Western) diet." (PMID 26055940, 2014). "We have tested if GLO1 overexpression can protect against accelerated atherosclerosis in STZ‐treated apolipoprotein E‐deficient (Apoe−/−) mice and if GLO1 knockdown can promote atherogenesis in nondiabetic Apoe−/− mice." (PMID 24920125, 2014). "In one study, long-term treatment with bone marrow-derived EPCs from young non-atherosclerotic Apolipoprotein E (ApoE) knockout mice prevented atherosclerosis progression in ApoE knockout recipients despite persistent hypercholesterolemia." (PMID 24736282, 2014). "In apoE knockout rats, occlusal disharmony may induce VCAM1, ICAM1 and TLR4 expression and accelerate the initiation of atherosclerosis." (PMID 25189624, 2014). "In contrast to vehicle treated non-diabetic ApoE−/−-mice, vehicle treated diabetic ApoE−/−-mice displayed more atherosclerosis in the aortic root." (PMID 23374104, 2013). "There are also reports that 5 mg/kg/d of PD123319 decreased atherosclerosis in diabetic apoE −/− mice, while 30 mg/kg/d of PD123319 did not affect systolic blood pressure in C57BL/6 mice infused with AngII 500 ng/kg/min." (PMID 23593499, 2013). "Interestingly, LPL (lipoprotein lipase, 1,001 fold), APOE (apolipoprotein E, 778 fold), FABP4 (fatty acid binding protein 4, 680 fold), and APOC1 (apolipoprotein C–I, 614 fold) are atherosclerosis related genes in which activated monocytes play a role." (PMID 23844045, 2013). "Still as the effect of APOE risk variants on CVD is small in the general population, our negative finding cannot rule out APOE as a risk factor for atherosclerosis and CVD in RA patients." (PMID 23613766, 2013). "In contrast, vitamin E treatment did not significantly change the amount of Cd8b protein in the atherosclerosis-prone aorta of ApoE−/− mice compared to untreated ApoE−/− mice." (PMID 23801967, 2013).
atherosclerosis (continued). "Second, although vinpocetine has shown its multifunction in vitro and in vivo by previous studies and our studies, the drawbacks of apoE-/- mice should be considered since it is not an accurate model of human atherosclerosis in light of plaque instability." (PMID 24349299, 2013). "Since a high-fat diet alone failed to develop atherosclerosis in wild-type mice (data not shown), we utilized ApoE−/− mice and subjected them to a high-fat diet." (PMID 23509822, 2013). "GO analysis of probe sets with significantly lower expression upon treatment compared to untreated ApoE−/− aortas detected that vitamin E and ACE inhibition prevented the up-regulation of muscle-specific genes in the atherosclerosis-prone aorta of ApoE−/− mice." (PMID 23801967, 2013). "Aldosterone was infused to achieve pathologically relevant levels that did not increase blood pressure in the atherosclerosis‐prone apolipoprotein E–knockout mouse (ApoE−/−)." (PMID 23525413, 2013). "Further, in macrophages obtained from ApoE mice, the cellular lipid content was lowered by 53% and uptake of oxidized LDL was reduced by 19%, suggesting that pomegranate byproduct significantly attenuated the development of atherosclerosis." (PMID 24077237, 2013). "In detail, the diminished progression of atherosclerosis, indicated by decreased lumen stenosis in GDF‐15−/−/apoE−/− mice, may be the consequence of alterations in apoptotic processes, proliferation, and number of MФ or SMC in atherosclerotic lesions." (PMID 23316317, 2012). "Systemic lack of HO-1 has been reported to promote atherosclerosis in ApoE null mice as well as aortitis in chow-fed old C57BL/6 mice, while its overexpression by adenoviral means results in decreased atherosclerotic lesions." (PMID 22833723, 2012). "Although considered to be a Th2 interleukin, IL-4 does not appear to be antiatherosclerotic, as IL-4−/− mice do not have increased atherosclerosis, and administration of IL-4 into ApoE−/− mice does not reduce development of atherosclerotic lesions." (PMID 22844641, 2012). "The data suggest that in the absence of apoE impaired LRP1 function correlates with improved atherosclerosis outcome." (PMID 22701627, 2012). "Determination of the in vivo significance of LDL receptor-related protein 1 (LRP1) dysfunction on lipid metabolism and atherosclerosis development in absence of its main ligand apoE." (PMID 22701627, 2012). "A point of support to this is the results by Hasty el al. who demonstrated in a model of viral apoE transduction that low levels of macrophage apoE expression that did not reduce plasma cholesterol in mice nonetheless retarded atherosclerosis development." (PMID 22606237, 2012). "Previous work from our laboratory indicated that supplementation of high fat, high cholesterol (1.25%, w/w) diets with CLA isomers did not alter atherosclerosis in the apoE−/− mouse." (PMID 23285120, 2012). "In the present study, we investigated the in vivo impact of LRP1 dysfunction on lipid metabolism and atherosclerosis development in the absence of apoE." (PMID 22701627, 2012).
atherosclerosis (continued). "BaffR.ApoE DKO and ApoE KO mice were fed a high fat diet (HFD) containing 21% fat and 0.15% cholesterol (Specialty Feed, Western Australia) for eight weeks to study the role of BAFF-R in atherosclerosis." (PMID 22238605, 2012). "The major findings of our study indicate that lack of eNOS reduces vessel wall oxidative stress in atherosclerosis despite accelerated plaque formation, increased vascular inflammation and L/E-interactions in apoE−/−/eNOS−/− vessels." (PMID 22291917, 2012). "FMT measurements with the αvβ3 integrin selective agent did not detect ezetimibe-induced inhibition of atherosclerosis progression in apoE−/− mice." (PMID 23119157, 2012). "The rapid onset and progression of atherosclerosis, CHD, and early death in hypercholesterolemic SR-BI/apoE dKO mice fed a normal chow diet and HypoE mice fed a standard Paigen or Paigen NC (this study) diet can be advantageous for a variety of studies of atherosclerotic CHD." (PMID 23112879, 2012). "Therefore, we used a complete GDF‐15 knockout mouse developed in our laboratory and crossbred it with apoE−/− mice, to study putative functions of GDF‐15 in atherosclerosis." (PMID 23316317, 2012). "Uncoupling of eNOS occurs in apoE−/− atherosclerosis but does not negate the enzyme's strong protective effects." (PMID 22291917, 2012). "We previously reported that atherosclerosis is accelerated in apoE−/−/eNOS−/− and that this increase in lesion formation is not secondary to increased blood pressure in this genotype." (PMID 22291917, 2012). "Although this model can explain the high prevalence of diabetes in atherosclerotic patients, we have not demonstrated the direct link between atherosclerosis and diabetes in the apoE-/- mice." (PMID 22204493, 2011). "As atherosclerotic cardiovascular disease is the leading cause of morbidity and mortality among patients with diabetes, apoE-/- mice are obviously a more suitable model for studying diabetes than mice that do not develop atherosclerosis." (PMID 22204493, 2011). "Intravenous administration of rAd.A20 to diabetic ApoE-null failed to protect from accelerated atherosclerosis, ruling out a systemic effect of A20 on the observed outcome." (PMID 21151899, 2010). "Our data show that ApoE−/− PGC-1α−/− and ApoE−/− PGC-1α+/+ mice do not differ with regard to atherosclerosis, features of plaque vulnerability, expression of VCAM-1, and T cells number." (PMID 21042583, 2010). "ApoE KO and PDZK1/apoE dKO mice were fed a high fat/high cholesterol diet supplemented with cholate (Paigen diet) for three months to study the consequences of PDZK1 gene inactivation on lipoprotein metabolism, atherosclerosis and coronary heart disease." (PMID 19956623, 2009). "Plaque rupture is not usually present in experimental atherosclerosis in animals including the apoE KO mice, which are considered an adequate experimental model for atherosclerosis studies." (PMID 19744321, 2009). "Importantly, when administered in vivo to ApoE−/− mice at a moderate dose, PCB-77 resulted in an increase in body weight, adipose mass and adipocyte area, serum cholesterol concentrations, and atherosclerosis." (PMID 18560532, 2008). "To prove the concept of iKO system, we generated ApoE iKO mice by creating ApoE KO line and ApoE TIGRE line separately and breeding them together, and attempted to model human conditions such as hypercholesterolemia and atherosclerosis." (PMID 18464897, 2008). "Furthermore, studies in apoE-/- mice show that these mice over-express MCP-1 and have accelerated atherosclerosis." (PMID 17210084, 2007). "Furthermore, elevated frequencies of TSCM cells have been observed in Treg lineage tracker-ApoE−/− mice, suggesting that increased TSCM levels could represent potential hallmarks of advanced atherosclerosis in murine models." (PMID 39940640, 2025).